IL2 (interleukin 2)
Diseases named in the same sentence as IL2 in open-access papers (continued):
Sharing a sentence is not in itself a finding about the gene and the disease.
acute lymphoblastic leukemia (10 papers, 2002 to 2025). Leukemia with an acute onset, characterized by the presence of lymphoblasts in the bone marrow and the peripheral blood. "In this study, we investigated the inhibitory effect of Allium senescens L. (A.S.)extract on cell survival and IL-2-mediated inflammation in human T cell acute lymphocytic leukemia (T-ALL) Jurkat cells." (PMID 33374788, 2020). "In this study, we evaluated the effect of A.S. extract on cell survival and IL-2 expression in human T cell acute lymphocytic leukemia Jurkat cells." (PMID 33374788, 2020). "The objective was also to compare saliva interleukin-2 concentration in relation to the Gingival Index (GI) reflecting condition of gums in children suffering from acute lymphoblastic leukaemia." (PMID 25976216, 2015). "Personalized low dose recombinant human IL-2-mediated NK cell stimulation represents an effective, nontoxic immunotherapy administered in the outpatient setting for relapsed acute lymphoblastic leukemia and warrants further investigation." (PMID 31245042, 2019). "Moreover, lower doses of IL-2 result in regulatory T cell expansion that may reduce immune responses, including NK cell anti-leukemia functions, and recent data revealed that IL-15 promotes B-acute lymphoblastic leukemia (ALL) cell expansion and their invasion of the central nervous system." (PMID 28555259, 2017). "Second, including the expression of IL-12 in the anti-CD19 CAR vector resulted in a significant increase in survival of mice bearing acute lymphoblastic leukemia (ALL), without the need for pretreatment or Il-2 support." (PMID 28331617, 2017).
allergic asthma (10 papers, 2014 to 2025). A asthma with a basis in a pathological type I hypersensitivity reaction. "In an experimental model utilizing mice, IL-2 is significantly elevated and can exacerbate allergic asthma through the toll-like receptor 9-IL-2 axis." (PMID 38967887, 2024). "IL-2 and IL-4 producing cells showed a significant decrease (P = 0.018 and P = 0.001, but in a steady fashion for IL-4), confirming the murine data about the potential beneficial effects of aerobic exercise for allergic asthma." (PMID 25050349, 2014). "We hypothesize that a neddylation inhibitor in combination with low dose IL-2 activation could be used to substitute for GRAIL and restore Treg function and stability in the Tregs of autoimmune and allergic asthma patients." (PMID 36569931, 2022). "Firstly, this study observed that the activity of peripheral blood Th1 cytokines (such as IL-2, IFN-γ) was significantly reduced, while the activity of Th2 cytokines (such as IL-4, IL-13) was significantly enhanced in children with acute exacerbations of allergic asthma." (PMID 40260311, 2025). "Our data showed the Lineage-cells from both mugwort-allergic asthma group and HDM-allergic asthma group could produce significant amounts of IL-5 and IL-13 after the stimulation with IL-33 when compared to IL-2 alone (all P < 0.05, respectively), or medium alone (all P < 0.05, respectively)." (PMID 29449864, 2018).
atrial fibrillation (10 papers, 2013 to 2025). A disorder characterized by an electrocardiographic finding of a supraventricular arrhythmia characterized by the replacement of consistent P waves by rapid oscillations or fibrillatory waves that vary in size, shape and timing and are accompanied by an irregular ventricular response. "Two patients developed cardiopulmonary symptoms during IL-2 therapy: one developed new onset atrial fibrillation that was associated with palpitations and one experienced chest pain." (PMID 35741162, 2022). "In the atrial fibrillation group, the ability of mDCs to stimulate T cells to secrete IL-2 and IFN-γ was significantly higher, and the ability to secrete IL-10 was significantly lower compared with the control group (P < 0.05)." (PMID 35600045, 2022). "If the supraventricular arrhythmia can be converted to NSR quickly or the heart rate and blood pressure managed despite atrial fibrillation, then consideration could be given to resuming IL-2 treatment." (PMID 31546315, 2014). "Interestingly and closely related with our results, IL-2 was able to induce in vitro the expression of SCN3B and sodium current density, increasing of atrial action potential duration and IL-2 has been linked to prognosis for atrial fibrillation in patients." (PMID 28327099, 2017). "Plasma levels of inflammatory cytokines of IL‐2, IL‐4, IL‐10, TNF, and IFN‐γ were reduced upon rivaroxaban treatment compared to warfarin in atrial fibrillation patients, with levels still slightly higher than controls." (PMID 40292918, 2025). "After α interferon upregulated PD-L1 expression in cells, the ability of mDCs to stimulate T cells to secrete IL-2, IL-10, and IFN-γ cytokines was reversed in patients in the atrial fibrillation group, and the differences compared with the control group were not statistically significant (P > 0.05)." (PMID 35600045, 2022). "Patients may continue IL-2, if SVT or atrial fibrillation are converted/controlled, sinus rhythm is maintained or heart rate is controlled and there are no signs of cardiac damage." (PMID 31546315, 2014).
cyst (10 papers, 2015 to 2024). A sac-like closed membranous structure that may be empty or contain fluid or amorphous material. "Proinflammatory cytokines IL-1β, TNF-α, and IL-2 were identified in the cyst fluid of human APKD kidneys." (PMID 39768851, 2024). "The levels of IFN-γ, IL-1β, IL-2, IL-4, IL-10, IL-12, and IL-13, in contrast, were significantly higher in pus than in cyst fluid." (PMID 35965529, 2022). "All these data suggest that only the response to E. granulosus antigens as AgB-specific triple functional IL-2+TNF-α+Th2+ cytokines and double functional TNF-α+Th2+ cytokines CD4+ T-cells associated with cyst biological activity." (PMID 26575186, 2015). "In conclusion, we demonstrated, for the first time, that polyfunctional T-cells subsets as IL-2+TNF-α+Th2+ triple-positive and TNF-α+Th2+ double-positive specific T-cells associate with biological cyst activity." (PMID 26575186, 2015). "We demonstrate that IL-2+TNF-α+Th2+ triple-positive AgB-specific CD4+ T-cells and TNF-α+Th2+ double-positive AgB-specific CD4+ T-cells associate with cyst biological activity, being significantly increased in the active CE stages." (PMID 26575186, 2015). "We demonstrate, for the first time to our knowledge, that polyfunctional T-cell subsets as IL-2+TNF-α+Th2+ triple-positive and TNF-α+Th2+ double-positive specific T-cells associate with cyst biological activity." (PMID 26575186, 2015). "Our data imply that the higher levels of IL-2 in the ABZ-CS-MPs treated group compared with the ABZ-T treated group may be responsible for more intensive inhibition of the cyst growth." (PMID 26352932, 2015). "Drainage can reduce the pressure within the cyst and even remove the adverse factors that hinder the healing, such as PGE2, lysosomes, toxic free radicals, and interleukin-2." (PMID 33435945, 2021). "For cyst type CE3 in Year 3, levels of IL-17A, IL-8, IL-1β, MIP-1α and MIP-1β were slightly elevated relative to those in CE4 in Year 2 whereas IL-2, TNF-α, IL-1Rα and G-CSF maintained stable levels." (PMID 32171321, 2020).
encephalitis (10 papers, 2020 to 2025). An acute inflammatory process affecting the brain parenchyma. "Alteration of CCL-4, CCL-17, CCL-20, CXCL10, CXCL-13, and TNF-α, IFN-γ, IL-2, IL-4, IL-5, IL-6, IL-9, IL-10, and IL-22 have been reported in the CSF or serum/plasma of patients with encephalitis." (PMID 40717731, 2025). "Blocking the interactions in the PD‐1/PD‐L1 pathway between CD8+ T cells and either astrocytes or microglia resulted in increased IFN‐γ and IL‐2 production in murine cytomegalovirus‐induced encephalitis." (PMID 37697956, 2024). "In experimental models, Th2 cytokines (IL-2, IL-4, IL-5, and IL-10) protected JEV-infected mice against viral encephalitis, and high CSF IL-10 levels were associated with protection against brain damage." (PMID 33776990, 2021). "Three studies with 176 encephalitis patients and 83 controls reported CSF concentration of IL-2." (PMID 36048783, 2022). "Various inflammatory cytokines/chemokines, such as IL-6, IL-17A, CXCL13 in cerebrospinal fluid, and IL-2 in plasma, and miRNAs (like e.g., Let-7b) in plasma, have been shown to play important roles in the process of anti-NMDAR encephalitis." (PMID 40948637, 2025). "The alteration in the concentration of the different chemokines, such as CXCL10, CXCL-13, CCL-4, CCL-17, CCL-20, and cytokines, including IL-2, IL-4, IL-6, IL-9, IL-10, and IFN-γ have been observed in encephalitis patients." (PMID 36048783, 2022). "Other markers (e.g., IL6, TNFA, IL2 and IL4) were also up-regulated and are increased in the CNS of patients with viral encephalitis and autoimmune epilepsy." (PMID 32225060, 2020). "Similarly, elevated levels of IL-1β, IL-2, IL-6, IL-8, IL-15, IL-17, and IL-18 have been detected in cases of GBS, active MS, encephalitis, inflammatory myopathies, viral and bacterial meningitis, and stroke." (PMID 40717731, 2025). "Although the overall concentration of the IL-2 was higher in encephalitis patients, this difference was not significant, with a P-value of 0.05 (SMD, 0.82; 95% CI, -0.02–1.66)." (PMID 36048783, 2022). "IL-2, CXCL10, CCL3, IL-10, CCL22, and IL-6 may represent new biomarkers in patients with anti-NMDAR encephalitis." (PMID 33408682, 2020).
Hashimoto thyroiditis (10 papers, 2015 to 2025). An autoimmune disorder caused by the production of autoantibodies against thyroid tissue. "In clinical studies, XYSJW has demonstrated a significant ability to reduce the levels of IFN-γ, IL-2, and IL-6 while increasing IL-10 levels in patients with Hashimoto’s thyroiditis and chronic lymphocytic thyroiditis, thereby regulating the Th1/Th2 balance." (PMID 40584613, 2025). "In Hashimoto thyroiditis, the serum levels of IL-2, IL-18, and IFNγ are higher in these patients." (PMID 40429402, 2025). "Cytometric Bead Array (CBA) analysis of pro and anti-inflammatory cytokines (IFN-gamma, IL-2, IL-6, IL-17 A, TNF-alpha and IL-4, IL-10) was done in 15 PTC irrespective of Lymphocytic Thyroiditis (LT) and 16 Hashimoto’s Thyroiditis (HT) cases." (PMID 37563607, 2023).
kidney damage (10 papers, 2014 to 2025). "In addition to causing kidney damage by inducing the proliferation of immune cells, IL-2 has been reported to regulate TECs directly, leading to kidney injury." (PMID 35971094, 2022). "Two studies demonstrated that a carefully adjusted, prolonged low-dose IL-2 treatment led to the recovery of TFR/TFH immune balance and successfully mitigated pathogenic B cell responses, as well as kidney damage." (PMID 36293075, 2022). "In lipopolysaccharide (LPS) nephropathy, which represents a model of transient proteinuria, the Treg level was modulated by the administration of IL-2/anti IL-2 immunocomplexes, resulting in a transient protective effect on proteinuria." (PMID 34792685, 2021). "More investigation is also needed to clarify the detail mechanism of increased IL-2 involved in kidney damage and microbiome alteration." (PMID 29492783, 2018). "They compared the effects of IL2 alone or combined with IL2-Ab in mice with LPS nephropathy showing superiority of IL2 alone to reduce proteinuria and renal damage." (PMID 26413873, 2015). "LPS nephropathy was inhibited by co-infusion of human IL-2, in which case proteinuria was reduced at each phase of the disease (7 mg/dl at 24 hours after LPS, 4,8 mg/dl at 48 hours and 0,8 mg/dl after 72 hours)." (PMID 25343479, 2014). "Our results indicate that IL-2-mediated inflammation could play a role in kidney damage, which was demonstrated also in adult studies but has not been researched extensively in the paediatric population." (PMID 40426748, 2025). "IL-2 is involved in the proliferation of T cells and natural killer (NK) cells in the immune system, and may indirectly lead to kidney damage." (PMID 35971094, 2022). "This suggested that TSF could adjust the renal level of IL-2 to an appropriate standard to improve renal immunity in db/db mice, eventually reducing the kidney damage." (PMID 29682583, 2018). "In this study, we thought to define whether Tregs can modify the outcome of LPS nephropathy utilizing IL-2 as inducer of tissue and circulating Tregs." (PMID 25343479, 2014). "Additionally, the significant elevation in IL-2 level was also noted in patients with nephropathy." (PMID 30881587, 2019). "While serum levels of IFN-γ, IL-2, IL-4, and IL-12 did not display a difference between experimental groups (data not shown), expression of IL-5, IL-6, TNF-α, IL-10, CXCL1, and IL-1β was elevated in the NZM2410/J mice displaying signs of severe kidney damage." (PMID 28491039, 2017).
leukocytosis (10 papers, 2017 to 2026). "In a typical inflammatory response model, interleukin-6 (IL-6) and tumor necrosis factor-alpha (TNF-α) are produced first, followed by an increase in interleukin-2 (IL-2) and interleukin-1α (IL-1α), which may lead to leukocytosis due to neutrophilia in the systemic circulation and immunosuppression." (PMID 38918542, 2024).
leukopenia (10 papers, 2012 to 2023). "In vivo experiments showed that APS-II can improve the leukopenia caused by cyclophosphamide and increase the IL-2, IL-4, and INF-γ levels in mice sera." (PMID 33390949, 2020). "The immunosuppression resulted in body weight loss, leukopenia and reduced IL-2 production by spleen cell cultures." (PMID 30671026, 2018).
macrophage activation syndrome (10 papers, 2014 to 2025). A complication of rheumatic disease that is caused by excessive activation and uncontrolled proliferation of T lymphocytes and well-differentiated macrophages. "Cytokine storm, defined as macrophage activation syndrome (MAS), is characterized by the release of multiple pro-inflammatory cytokines (IL-1β, IL-18, IL-6, IL-2, IL-7, TNF-α) and chemokines (CCL2, CCL3) from macrophages." (PMID 35008658, 2021). "These two studies also suggested that the cytokine profile associated with hemophagocytic lymph-histiocytosis/macrophage-activation syndrome (HLH/MAS) mirrors the cytokine profile observed in severe CRS and that IL-2, which is released only by T cells, does not associate with CRS severity." (PMID 32426136, 2020).
ovarian tumor (10 papers, 2013 to 2025). "After ex vivo stimulation of the dissociated tumor tissue with ETA-067 and IL-2, we observed 70% lysis of ovarian tumor cells by ETA-067–stimulated Vδ2 TIL." (PMID 40755782, 2025). "Using anti-CD3/anti-CD28 Dynabeads and high-dose IL-2, TILs were expanded from 89.7% of surgically resected ovarian tumours." (PMID 30039427, 2018). "In this preclinical study, we investigated the efficacy of using anti-CD3/anti-CD28 magnetic beads and IL-2 to expand TILs from freshly resected ovarian tumours." (PMID 30039427, 2018). "The increased levels of IL-2 and IFN-γ as well as the CD3+ T cell proportion in the antibody-secreting CAR-T-cell group suggested that the secreted forms of antibodies increased the immune response of MSLN CAR-T cells against ovarian tumor xenografts." (PMID 39431011, 2024). "We evaluated numerous cell types, including IL-2 expanded T cells, CD14+ derived monocytes, but chose adipose tissue derived MSC due to their ability to be infected by MV and co-localization with ovarian tumors." (PMID 23347343, 2013). "Moreover, PBL or TIL of patient OC11 were co-cultured with autologous primary ovarian tumor cells OC11 in the presence or absence of 1 μg/mL tribody [(HER2)2xCD16] together with IL-2." (PMID 29725336, 2018). "NK cell infusion reduced the growth of ovarian tumors (no treatment vs NK + PBS, * p < 0.05), and the addition of rhIL-2 injection to facilitate NK efficacy led to more significant inhibition of tumor growth (no treatment vs NK + IL-2, *** p < 0.001)." (PMID 37041591, 2023).
periodontal disease (10 papers, 2018 to 2025). "RA patients had a higher bacterial load, a more diverse microbiota, an increase in bacterial species associated with periodontal disease, more clinical attachment loss, and increased production of inflammatory mediators including IL-17, IL-2, TNF, and IFN-γ." (PMID 31182740, 2019). "Previous studies have shown that elevated levels of serum inflammatory markers, such as tumor necrosis factor-α, interleukin-6, interleukin-2, and C-reactive protein, are associated with an increased risk of AF and are commonly found in patients with periodontal disease." (PMID 37420240, 2023). "During the periodontal disease progression, circulating levels of pro-inflammatory cytokines increase, including interleukins (IL-1β, IL-2, IL-6, IL-8)." (PMID 37936877, 2023). "Patients with periodontal disease showed higher levels of cytokines (IL-2, IL-6, IL-10, and TNF-α) and PGE2." (PMID 30154640, 2018). "Therefore, the objective of this work was to analyze the cytokines IL-2, IL-6, IL-10, and TNF-α and inflammatory mediators such as PGE2 in pregnant patients at risk of preterm delivery and their relationships with periodontal disease." (PMID 30154640, 2018). "Furthermore, other downstream cytokines, including IL-2, IL-8, TNF-α, and IL-13, were also statistically significantly (p < 0.05) increased as periodontal disease severity increased, supporting a heightened inflammatory response." (PMID 41303313, 2025). "Similarly, a study showed that higher levels of IL-2, IL-6, IL-10, TNF-α, and PGE2 were detected in the serum of preterm women with periodontal disease, while the serum levels of IL-2, IL-6, and IL-10 were higher in high-risk preterm women than in low-risk preterm women." (PMID 36388896, 2022).
rheumatic diseases (10 papers, 2021 to 2025). "In 2023, our team analyzed 18 studies around the world on the percentage of Treg cells in patients with rheumatic disease with Ld IL-2 and concluded that Ld IL-2 treatment increases the proportion of Treg cells." (PMID 39981233, 2025). "The IL-2 pathway plays a pivotal role in Treg response and holds significance in rheumatic diseases." (PMID 38954480, 2024). "It is evident that several rheumatic diseases display elevated serum levels of inflammatory cytokines, such as IL-2, IL-6, TNF-α and markers of systemic inflammation." (PMID 37681925, 2023). "Summary of results from clinical studies with low-dose IL-2 therapy in autoimmune and rheumatic diseases." (PMID 33868284, 2021). "Here we highlight key findings and summarize recent advances in the clinical translation of low-dose IL-2 therapy for the treatment of autoimmune and rheumatic diseases." (PMID 33868284, 2021). "These could include the administration of exogenous IL-2 to reverse Treg dysfunctionality, as pioneered in other rheumatic diseases, or the use of PD-1-stimulating antibodies to restore the immune checkpoint." (PMID 38334659, 2024). "Potentially, low-dose IL-2 administration may be a beneficial treatment for people with SS and other rheumatic diseases." (PMID 35526080, 2022). "The EULAR/ACR/PRINTO criteria, which was originally developed for patients with juvenile idiopathic arthritis, has been suggested for use in adult patients with rheumatic disease, considering that soluble IL-2 and NK-cell activity are not routinely accessible in most hospitals." (PMID 35522672, 2022). "There are no drugs that directly inhibit IL-2 or IL-2R in rheumatic diseases." (PMID 35296071, 2022).